RNU7-51P (RNA, U7 small nuclear 51 pseudogene)
Synonyms: U7.51
Gene: Small nuclear RNA gene on chromosome 14 (83,048,579 to 83,048,640, forward strand). Ensembl gene ENSG00000252369.
Homologues: Orthologues: chimpanzee U7 (98% identical), macaque U7 (92% identical). Paralogues in human: RNU7-19P (84% identical), RNU7-73P (84% identical), RNU7-1 (82% identical), RNU7-14P (82% identical), RNU7-187P (82% identical), RNU7-3P (82% identical), RNU7-4P (82% identical), RNU7-7P (82% identical), RNU7-20P (81% identical), RNU7-24P (81% identical), RNU7-2P (81% identical), RNU7-47P (81% identical), and 141 more.